EGFR (epidermal growth factor receptor)
Diseases named in the same sentence as EGFR in open-access papers (continued):
Sharing a sentence is not in itself a finding about the gene and the disease.
glioma (continued). "EGFR amplification is seen in approximately 50% of GBM, and in approximately 50% of those tumors the glioma cells express EGFRvIII, a mutant receptor that persistently activates downstream immunosuppressive pathways including those involving STAT3." (PMID 23737783, 2013). "Because this question cannot be readily determined in xenograft tumors in situ, we have addressed this question in cell culture, using well-defined pharmacological treatments and three human glioma lines: U87MG, U87+EGFR, and U87+EGFRvIII." (PMID 24039668, 2013). "This modulatory effect of NOTCH3 can be predominantly attributed to NOTCH target genes as well as its potential cooperation with major aberrant signaling pathways in malignant glioma such as EGFR, C-MYC and CCND1, which are all often altered in glioma." (PMID 24143218, 2013). "In general, tyrosine kinase receptors (EGFR, PDGFR, FGFR, Met-receptor) have been much studied in gliomas." (PMID 23998913, 2013). "Together, these findings suggest that NOTCH3 is highly likely to induce glioma cell invasion and proliferation via at least the activation of CCND1, cMYC and EGFR gene expression." (PMID 24143218, 2013). "We decided to investigate the NFKBIA status in relationship to EGFR in primary GBM and in GBM stem-like cells, a highly tumorigenic subpopulation exploiting stem cell programs for glioma perpetuation." (PMID 24330732, 2013). "These initial findings again position TAMs within a potential paracrine network with glioma cells, acting to reinforce expression of both EGF and EGFR on glioma cells to promote tumor progression." (PMID 23737783, 2013). "A paracrine mechanism driven by Delta-EGFR, with secretion of IL-6 and LIF was shown to recruit wild-type EGFR-expressing glioma cells into accelerated in vivo proliferation." (PMID 23998913, 2013). "The frequency of EGFR immunopositivity was significantly higher in grade III and IV gliomas compared with grades I and II." (PMID 23946790, 2013). "The frequency of EGFR immunopositivity was significantly higher in the grade III and IV gliomas than in the grade I and II gliomas (P=0.021)." (PMID 23946790, 2013). "Epidermal growth factor receptor (EGFR), an important receptor of EGF with high affinity, was often overexpressed in glioma cells." (PMID 22829952, 2012). "It seems that EGFR and MGMT promoter hypermethylations are early events in the clonal evolution of gliomas and this gene inactivation has proved to be stable even in tumour recurrence." (PMID 22264301, 2012). "EGF/EGFR signalling through extracellular signal-regulated kinases 1/2 (ERK1/2) and casein kinase-2 (CK2) in glioma cells results in the phosphorylation of α-catenin at serine 641, which correlates with glioma malignancy." (PMID 22400111, 2012). "FISH analysis for mouse EGFR of eleven murine gliomas containing large regions of recruited cells with high expression of EGFR and/or IGFR showed >2 copies of EGFR in 5 of 11 cases, while 1 of 11 showed >2 copies of IGFR." (PMID 21754979, 2011).
glioma (continued). "We then characterized tumors with regions dominated by recruited cells for expression of growth factor receptors commonly activated in human gliomas, including PDGFR, EGFR and IGFR." (PMID 21754979, 2011). "Among the significant correlation changes in the network, we find three genes (MYT1L, EGFR, POSTN) known to have meaningful roles in glioma pathogenesis." (PMID 21756334, 2011). "In glioma cells that were treated by exogenous EFEMP1 protein or over-expressed endogenous EFEMP1, the EGFR level was reduced and AKT signaling activity attenuated." (PMID 21955618, 2011). "These include epidermal growth factor (EGF), platelet-derived growth factor (PDGF), insulin-like growth factor 1 (IGF-1), and their specific receptors (EGFR, PDGFR, and IGFR), all of which are involved in autocrine or paracrine signaling in gliomas." (PMID 22091432, 2011). "In a survey of 15 established human glioma tissue cell lines we observed that binding of QD-EGF varied considerably, consistent with the known variability of wildtype and mutant EGFR expression in gliomas." (PMID 20614029, 2010). "Living glioma and normal cells or tissue biopsies were incubated with QDs coupled to EGF and/or monoclonal antibodies against EGFR for 30 minutes, washed and imaged." (PMID 20614029, 2010). "The data presented here show highly specific labeling of native human glioma biopsies that can be distinguished from normal brain tissue down to the single cell level by staining with QD-EGF and/or QD-MAb anti-EGFR." (PMID 20614029, 2010). "For example, it is well established that both epidermal growth factor receptor (EGFR) and the phosphatidylinositol 3-kinase (PI3K)/Akt pathways play a major role in the pathogenesis of human gliomas." (PMID 20975961, 2010). "For example, EGFR is generally considered as the driver gene at 7p11, however, SEC61G is recurrently co-amplified and over-expressed in glioma." (PMID 21170331, 2010). "The obvious marker for our QD probe was the epidermal growth factor receptor (EGFR or Her1), upregulated in many head and neck tumors and an established target for glioma therapy." (PMID 20614029, 2010). "The EGFR mutant vIII lacks the EGF binding site but is constituitively active and is expressed in ∼60% of high-grade gliomas EGFR." (PMID 20614029, 2010). "Growth factor pathways, such as epidermal and vascular epithelial growth factor receptors (EGFR, VEGFR) play a significant role glioma cell proliferation, migration, and neovascularization." (PMID 19777070, 2009). "Our data argue that Cdk4 activity is a key tumor-specific rate-limiting output of EGFR and PI3K signaling in glioma as well." (PMID 19214224, 2009). "Dap is highly regulated in a cell-type specific manner, and studies of Dap regulation in glia may further illuminate the genetic origins of glioma, especially given that lack of p21 expression may underlie the tumorigenic response of mammalian glial progenitors to constitutively active EGFR." (PMID 19214224, 2009). "Since concurrent activation of EGFR-Ras and PI3K signaling in glial precursors induces glioma in the mouse, we sought to create mutant phenotypes by hyperactivation of these pathways in fly glia and glial precursors." (PMID 19214224, 2009). "Based on a set of gliomas analyzed by CGH-array, we selected tumors displaying one of these two characteristics and mutually exclusive patterns -1p19q codeletion or EGFR amplification- and compared their gene expression profiles." (PMID 18492260, 2008). "Amplification of the oncogene EGFR and deletion of the tumor suppressor PTEN have been identified as the critical genetic changes in the tumorigenesis of human GBMs or other types of glioma." (PMID 18940013, 2008). "The model tested the following covariates: age, glioma gene signature, and expression status of MGMT, VEGF, and EGFR." (PMID 18940004, 2008).
glioma (continued). "This confirms previously reported observations of differential inhibition of EGFR and MAPK phosphorylation in glioma cell lines and shows the effectiveness of gefitinib against EGFR signaling in human keratinocytes." (PMID 16306877, 2006). "EGFR activation increased nuclear FABP7 immunoreactivity in a glioma cell line in vitro, and inhibition of FABP7 expression suppressed EGF-induced glioma-cell migration." (PMID 16623952, 2006). "A truncated and constitutively activated form of EGFR, EGFRvIII, is also frequently seen in glioma and is able to increase VEGF expression in glioma cells." (PMID 15305185, 2004). "In gliomas, ZC3H15 suppresses CBL expression, thereby enhancing EGFR protein stability." (PMID 41513632, 2026). "Notably, chimeric antigen receptor (CAR)-engineered NK cells targeting EGFR, HER2, GD2, and CD133 show promise in preclinical glioma models due to their enhanced specificity and reduced toxicity compared to CAR-T cells." (PMID 41929521, 2026). "Furthermore, a circular E-cadherin RNA (circ-E-Cad) encodes a secretory E-cadherin protein variant (C-E-Cad), which promotes GBM tumorigenesis by binding to the EGFR CR2 domain and maintaining glioma stem-cell tumorigenicity." (PMID 40723354, 2025). "Notably, chromosomal 7+/10− alterations (encompassing EGFR and PTEN loci) were rare in IDH1/2-mutant gliomas (1.0% in high-grade gliomas)." (PMID 41377022, 2025). "Through dividing the samples into high and low SASP Score groups using the median SASP Score as a threshold, we observed more EGFR (26.67%), PTEN (27.14%), and NF1 (10%) mutations in the high SASP Score group than low SASP Score group (EGFR (1.90%), PTEN (0.95%), NF1 (4.76%)) of glioma." (PMID 40781221, 2025). "Notably, IGFBP2 is an established oncogene in various tumors including myeloid leukemia, gliomas, breast, and prostate cancer, and orchestrates multiple cancer signaling pathways such as PI3K-AKT, NF-κB, and EGFR/STAT3." (PMID 40193528, 2025). "Hyperactivation of the epidermal growth factor receptor (EGFR) signaling pathway, often due to gene amplification, and inactivation of the PTEN tumor suppressor gene are the main drivers of the aggressive phenotype of high-grade gliomas." (PMID 41304780, 2025). "Expression of serotonin receptor (5-HT7R) in a Drosophila glioma model, which mimics human glioma via co-expression of active PI3K and EGFR in glial cells, reduced larval lethality, restored normal brain morphology, and reversed molecular markers altered in gliomas." (PMID 40565099, 2025). "The prognosis of gliomas is significantly affected by these molecular alterations, such as whether IDH1, IDH2, EGFR, CDKN2A, and CDKN2B are altered for adult‐type gliomas, and whether H3 K27 and H3 G34 are altered for pediatric‐type gliomas." (PMID 39804195, 2025). "It has also been used to detect complex CNVs such as JAK1-PAK2, JAK1-PVT1, JAK1-MYOCD, JAK1-TIMM21, USP7-TIMM21, and JAK1-Chr22 CNVs in whole blood-derived ovarian cancer samples, EGFR, CDKN2A, and BRAF CNV in glioma tissues, as well as FGFR2 CNV in colorectal and gastric adenocarcinomas." (PMID 40725150, 2025).
glioma (continued). "EGFRvIII is commonly expressed in gliomas and other tumors but is absent in normal tissues, whereas EGFR is found in normal tissues but exhibits elevated expression levels in cancers." (PMID 40895575, 2025). "Among all RTKs, the epidermal growth factor receptor (EGFR) and vascular endothelial growth factor receptor (VEGFR), along with their ligands, are considered to play a special role in the pathogenesis of gliomas." (PMID 40428422, 2025). "Finally, we selected the following seven indicators as the mIHC panel: IDHR132H, ATRX, EGFR, CDKN2A, HIP1R, GFAP (glial fibrillary acidic protein, marker of glioma cells), and DAPI (4ʹ,6‐diamidino‐2‐phenylindole, marker cell nucleus)." (PMID 40264576, 2025). "Other targeted therapies or combinations of therapies for glioma have not made significant progress: tyrosine kinase inhibitors targeting the EGFR alone or in combination with TMZ failed to significantly improve prognosis." (PMID 39950738, 2025). "As a humanized monoclonal antibody, Nimotuzumab has a high affinity and can bind to the extracellular domain of EGFR and inhibit EGF binding Nimotuzumab has been approved in several countries for the treatment of HNSCC and glioma based on clinical trials of various malignancies." (PMID 39183296, 2024). "Although the effect of WZ-3146 on glioma has not been reported, WZ-3146, as an EGFR inhibitor, can significantly inhibit the growth of pancreatic cancer." (PMID 38937742, 2024). "Moreover, NGS of glioma is now justified to look for CDKN2A/B homozygous deletions that upgrade IDH-mutant astrocytomas to grade IV, and EGFR amplification, chromosome (+ 7/-10) and TERT promoter mutations that upgrade IDHwt astrocytomas to grade IV." (PMID 39361075, 2024). "Lastly, cell signaling pathways, such as the epidermal growth factor receptor (EGFR), PI3K-AKT, and RAS-MAPK, are significantly involved in the progression of glioma, influencing cell growth, survival, and proliferation." (PMID 39144445, 2024). "NEC gliomas are IDH1 non-mutant gliomas that express ATRX, lack necrosis or microvascular proliferation, and do not have chromosome 7 gain, chromosome 10 loss, EGFR amplification, or TERT promoter mutation." (PMID 39135755, 2024). "EGFR‐AMPK signaling has been documented to enhance telomerase activity and sustain telomere length, consequently stimulating the proliferation and immortalization of glioma cells." (PMID 39722126, 2024). "EGFR signaling is clinically relevant and therapeutically targetable in low-grade gliomas as well as other brain and non-brain malignancies, and so we sought to further characterize APA of genes involved in EGFR signaling pathways." (PMID 39375704, 2024). "This indirect evidence preliminarily proves that WZ-3146 may suppress EGFR expression, ultimately inhibiting KIF4A expression, in glioma." (PMID 38937742, 2024). "It is anticipated that further investigation into TRIB3 and AURKA could lead to the development of novel therapeutic targets for glioma, such as MGMT and EGFR." (PMID 39118481, 2024). "The engineered cells showed in vitro efficacy against mutant EGFR and not wild-type EGFR-expressing glioma cell lines." (PMID 38486856, 2024). "EGFR amplification is not detected in other glial tumors with a better prognosis, as it has great specificity for very aggressive gliomas." (PMID 39057054, 2024). "The involvement of PAK4 in anoikis resistance was confirmed by its experimental silencing, which led to increased anoikis and inhibition of glioma cell invasion and migration through downregulation of metalloprotease 2 (MMP2), alpha-v beta-integrin (Avß3) and epidermal growth factor receptor (EGFR)." (PMID 39062119, 2024). "For glioma, the focus was on combining PDT with clinically accepted EGFR inhibitors." (PMID 39201395, 2024).
glioma (continued). "Later, attempts were made to introduce oncogenes such as EGFR and CDK4 by somatic cell gene transfer using viral vectors based on replication-competent avian leukosis virus splice acceptor (RCAS) and their TVA receptors to generate glioma models." (PMID 39768176, 2024). "Variant III (EGFRvIII) is the most common gene mutation of epidermal growth factor receptor (EGFR) and it is present in about 52% of glioma cells, but not in normal tissues." (PMID 36831396, 2023). "The specific targeting of EGFR-overexpressing cells has been achieved by using the monoclonal antibodies (mAbs) Cetuximab and L8A4 which target EGFR overexpressed in tumors such as gliomas, bearing up to 1000 boron atoms." (PMID 37444386, 2023). "Another analysis of health-related quality of life (HRQoL) showed depatux-M had no impact on HRQoL in EGFR-amplified recurrent-glioma patients." (PMID 37444531, 2023). "In an immunocompetent host, the combination of OV-IL15C and EGFR-CAR NK significantly enhanced endogenous NK and CD8+ T-cell infiltration, improved the persistence of EGFR-CAR NK-cells within the tumor site, and prolonged the survival of glioma-bearing mice." (PMID 38136398, 2023). "Afatinib (a second generation of EGFR-inhibitor) combined with TMZ synergistically inhibited cell proliferation, clonogenicity, invasion and motility of cultured glioma cells expressing EGFRvIII and prevented progression of intracranially implanted U87-MG EGFRvIII cells." (PMID 36900355, 2023). "Furthermore, through activation of tumour growth factor beta (TGF-β) and epidermal growth factor receptor (EGFR) signalling pathways, glioma cells can enhance their invasiveness." (PMID 37686020, 2023). "IFI30‐mediated EGFR/AKT/GSK3β/β‐catenin signaling not only promotes the epithelial–mesenchymal transition‐like phenotype by upregulating the expression of Slug, but also subsequently enhanced invasion and chemoresistance of glioma cells." (PMID 37408388, 2023). "Moreover, the exploration of various molecular targets, such as EGFR, EGFRvIII, miRNAs, MET, and other signaling pathways, underscores the complex nature of glioma and the potential for targeted therapies." (PMID 38002561, 2023). "Moreover, PDGFRA is co‐expressed with EGFR and EGFR amplification requires PDGFRA signaling to promote the development of glioma." (PMID 36043552, 2023). "Although both circ-EGFR and TUSC2 protein expression are low in glioma samples, overexpression of circ-EGFR significantly increased TUSC2 protein expression and promoted TUSC2-mediated inhibition of glioma proliferation, migration and survival in vitro and in vivo." (PMID 37173921, 2023). "Also, the combined treatment of nimotuzumab, a monoclonal antibody against epidermal growth factor receptor (EGFR), and rapamycin, an mTOR inhibitor, achieved more efficient outcomes than TMZ treatment on patient-derived human glioma cells." (PMID 37144620, 2023). "Although, association between EGFR mutation and PD-L1 expression has been observed in other cancer type such as, NSCLC69, this phenomenon has not been elucidated in gliomas." (PMID 36720864, 2023). "Consequently, the EGFR expression level increases, inducing upregulation of PKM2 via NF-κB activation, thus contributing to glioma tumorigenesis." (PMID 37371047, 2023). "Amplification of EGFR and CDK4—both known oncogenes—has also been observed in APOBEC3-high gliomas." (PMID 36978147, 2023). "This glioma cell line overexpresses several genes similar to those reported for human gliomas, such as the PDGFβ, insulin-like growth factor (IGF)-1, epidermal growth factor receptor (EGFR), and Erb3/Her3 precursor proteins." (PMID 37512530, 2023).